SNORD11B (small nucleolar RNA, C/D box 11B)
Gene: Small nucleolar RNA gene on chromosome 2 (202,291,332 to 202,291,421, forward strand). Ensembl gene ENSG00000271852.
Gene Ontology:
Biological process: RNA processing
Cellular component: nucleolus
Homologues: Orthologues: macaque SNORD11B (90% identical), pig SNORD11B (89% identical), guinea pig SNORD11B (83% identical), rabbit SNORD11B (82% identical), mouse Gm26287 (79% identical), rat Snord11b (74% identical).